INS (insulin)
Diseases named in the same sentence as INS in open-access papers (continued):
Sharing a sentence is not in itself a finding about the gene and the disease.
type 1 diabetes (continued). "Before the discovery of insulin, very low carbohydrate ketogenic diets, along with extended fasting, were non-pharmacological strategies to manage type 1 diabetes." (PMID 36676967, 2022). "Patients suffering with type 1 diabetes are solely dependent on external insulin injections for their survival and for maintaining a normal life, but it is not comfortable to inject insulin daily." (PMID 35268639, 2022). "Results from studies in non-pregnant populations suggest that automated insulin delivery systems can safely improve glycemia across age groups ranging from very young to older aged people with type 1 diabetes." (PMID 35382796, 2022). "Few RCT demonstrated that a dietary intervention based on standard nutritional recommendations or healthy dietary pattern improved glycemic control in adolescents with type 1 diabetes without changes in insulin dose." (PMID 35459205, 2022). "The insulin-dependent diabetes, which is often known as type 1 diabetes, is also a chronic disorder in which the pancreas produces little or no insulin on its own." (PMID 36232070, 2022). "Reportedly, 50%–70% of human type I diabetics that received pancreatic islet implants did not require insulin therapy 5 years after treatment." (PMID 35769100, 2022). "This is often not an issue in the periphery except in type 1 diabetes when pancreatic insulin secretion is low or absent." (PMID 35884888, 2022). "In a small study of nine male adults with type 1 diabetes, there was an increase in sCD163 during the early stages of ketoacidosis that was induced by lipopolysaccharide exposure and lack of insulin." (PMID 36404844, 2022). "In persons with type 1 diabetes (T1D), insulin secretion by the pancreas is absent because of the autoimmune destruction of the pancreatic beta cells, breaking the normal closed-loop regulation process." (PMID 35394448, 2022). "Type 1 diabetes is best treated by daily injections of insulin, substituting for the lack of the body’s own synthesis." (PMID 35216316, 2022). "Most patients with type 1 diabetes (T1DM) do not reach the blood glucose goal with treatment of insulin." (PMID 35872994, 2022). "Unlike before, they utilized glucose to promote insulin secretion through diffusion interacting with pancreatic β-cells loaded in MNP to treat type 1 diabetes." (PMID 36151726, 2022). "In type 1 diabetes (T1D), the autoantigens in the pancreas are presented by major histocompatibility complex (MHC) molecules that activate diabetogenic T cells and play important roles in the destruction of pancreatic insulin (Ins)-producing β cells." (PMID 36189304, 2022). "Autoantibodies against glutamic acid decarboxylase 65 (GAD65), tyrosyl phosphatase (IA-2), insulin (IAA) may prelude the onset of clinical manifestation of T1D for years, furthermore multiple islet autoantibodies are associated with highest risk of type 1 diabetes." (PMID 35784568, 2022). "Insulin intake in type 1 diabetes did not change from pre‐ to post‐training (151.90 ± 29.47 units Pre, 151.00 ± 29.44 units Post; P = 0.430)." (PMID 34995365, 2022). "Henceforth, in underdeveloped countries, a lower incidence and prevalence were found, where there is still a lack of insulin therapy due to the high prices of these medications, which poses a major problem in the management of type 1 diabetes." (PMID 36384715, 2022). "Type 1 diabetes (T1D) is an immune‐mediated disorder characterized by hyperglycemia resulting from a deficit or absence of endogenous insulin due to the destruction of pancreas beta cells." (PMID 35751499, 2022). "The current study has shown that suicides using insulin among insulin-dependent diabetics are equally as prevalent, if not more so than fatal accidental insulin overdoses." (PMID 35943711, 2022).
type 1 diabetes (continued). "T1D, once known as juvenile diabetes or insulin‐dependent diabetes, is a chronic condition in which the pancreas produces little or no insulin, a hormone that is necessary for survival because it allows glucose to enter cells to produce energy." (PMID 34612510, 2022). "Which strategy of insulin application suits best for individuals with type 1 diabetes to achieve good glycaemic control without hypoglycaemic events is debated." (PMID 34301317, 2021). "Studies exploring alternative methods of insulin delivery and the use of noninsulin anti-diabetic drugs as adjunct therapies in type 1 diabetes were considered particularly important." (PMID 33496671, 2021). "Safety and efficacy of the first commercially approved hybrid closed-loop system (Medtronic 670G insulin pump with Guardian 3 sensor) was evaluated in a non-randomised before-and-after study in 30 adolescents and 94 adults with type 1 diabetes, over 3 months." (PMID 33550442, 2021). "This also implies that ASTX treatment does not improve insulin secretion in type I diabetes patients." (PMID 34684576, 2021). "A similar relation in women with type 1 diabetes or insulin-treated GDM has been observed, but not in women with mild (diet-treated) GDM." (PMID 34151398, 2021). "This can be explained by the metabolic mechanism in which a patient with type 1 diabetes, who does not have his own insulin, is also deprived of endogenous regulation responsible for maintaining a constant level of glycemia." (PMID 33467392, 2021). "Alcohol and/or cocaine use in type 1 diabetes organ donors increases exocrine pancreas pathology and islet amyloid deposition but does not affect insulitis or insulin positivity." (PMID 34912300, 2021). "Type I diabetes is when the pancreas produces little or no insulin, the hormone that allows for glucose to enter cells from the bloodstream, leading to hyperglycemia." (PMID 33679974, 2021). "Type 1 diabetes, once known as juvenile diabetes or insulin-dependent diabetes, is a chronic condition in which the pancreas produces little or no insulin by itself." (PMID 33799983, 2021). "Unlike Type 1 Diabetes which is characterized by a deficiency of insulin, most individuals affected by T2DM have elevated insulin levels (fasting and/or post glucose ingestion), unless there has been beta cell failure." (PMID 34447776, 2021). "Although they recognized that reducing carbohydrate intake can reduce insulin requirements, some felt the need to state that type 1 diabetes requires insulin, regardless of diet." (PMID 33496671, 2021). "A recent study from India showed that glycaemic control in people with type 1 diabetes worsened during lockdown period mainly due to non-availability of insulin and glucose testing kits." (PMID 33067723, 2021). "In Type 1 Diabetes (TD1M), insulin analogues, both short-acting and long-acting, should always be offered as an option, which more closely reproduce the physiological needs and translate into a lower risk of hypoglycemia given the specific pharmacokinetics and pharmacodynamics of both preparations." (PMID 34572493, 2021). "Type 1 diabetes is a life-long disease characterized by the destruction of pancreatic beta cells and lack of insulin production." (PMID 34671071, 2021). "Diabetes is classified into two types: type 1 (insulin-dependent diabetes), which occurs as a result of the pancreas’ inability to secrete enough insulin due to beta cell destruction, and type 2 (non-insulin-dependent diabetes)." (PMID 34827553, 2021). "Severe hypoglycemia is a major obstacle to optimal management of type 1 diabetes with insulin and it is not just debilitating, it can be fatal, accounting for up to 10% of deaths in this population." (PMID 34444787, 2021). "The hallmark of type 1 diabetes (T1D) is an absolute lack of insulin." (PMID 34176476, 2021). "In type I diabetes, a lack of insulin prevents dextrose from entering the cells leading to impaired carbohydrate metabolism." (PMID 33530644, 2021).
type 1 diabetes (continued). "A “fear of needle injections”, an item on the Chinese Attitudes to Starting Insulin Questionnaire, was the most prevalent negative attitude towards starting insulin in 205/293 (70%) of patients with type 1 diabetes." (PMID 34111207, 2021). "Although it remains controversial whether SGLT2i can be combined with insulin to treat type 1 diabetes mellitus (T1DM) because of safety issues, recent meta-analyses of clinical trials have demonstrated a reduction in HbA1c levels of approximately 0.4% in patients with T1DM." (PMID 33827579, 2021). "In this study, the animal model we are using is an STZ-induced type 1 diabetic model with no excretion of insulin (STZ induces β cells destruction)." (PMID 34680477, 2021). "The derailed glucagon secretion is not confined to hypoglycemia as individuals with type 1 diabetes, as opposed to nondiabetic individuals display glucagon hypersecretion after meals, thereby potentially contributing to insulin resistance." (PMID 34405569, 2021). "Alternative inventions for designing better insulin delivery systems also failed to meet the clinical need to treating Type 1 diabetes, and hence, better approaches remain to be achieved for such a medical need." (PMID 34572086, 2021). "In non-obese mice with type 1 diabetes, it was further shown that substitution of insulin with leptin or supplementation of leptin instead of insulin therapy can mimic the effect of insulin monotherapy." (PMID 33808424, 2021). "In conclusion, swimming training does not affect the benefits of insulin treatment on the femoral midshaft structural and mechanical properties in growing rats with severe type 1 diabetes." (PMID 34440530, 2021). "T1D, formerly referred to as juvenile diabetes, is a form of diabetes in which little or no insulin is produced because autoimmunity destroys β cells of the islet of Langerhans in the pancreas." (PMID 34067503, 2021). "People with type 1 diabetes and hospitalization used similar insulin therapies as those without hospitalization." (PMID 34277957, 2021). "Type 1 diabetes is characterized by a lack of insulin production by the pancreas mostly due to the autoimmune-mediated destruction of pancreatic beta cell." (PMID 34830886, 2021). "In summary, intermittent use of FGM in T1DM patients can improve HbA1c and glycaemic control without increasing hypoglycaemic exposure in insulin-treated type 1 diabetes individuals in an developing country." (PMID 34907285, 2021). "Altogether, adult studies have identified a slight improvement in glycemic control, weight, and bolus insulin dose among patients with type 1 diabetes on combined therapy of insulin and GLP-1 agonists, but not DPP-4 inhibitors." (PMID 33828529, 2021). "Cells in type 2 (non-insulin-dependent) diabetes no longer respond to insulin and become insulin resistant." (PMID 34827553, 2021). "In streptozotocin-induced type 1 diabetic rats, oral administration of PCB/INS particles with diameter sub-200 nm, especially in capsules, significantly enhanced the bioavailability of insulin and achieved longer duration of hypoglycemic effect than the subcutaneously injected insulin." (PMID 33754071, 2021). "For example, the ASK-12 questionnaire has not been specifically validated in people with type 1 diabetes, and detailed information on the insulin regimen is lacking." (PMID 36994341, 2021). "Although PACAP is known to stimulate insulin secretion, it did not alter blood glucose levels in this model of type I diabetes." (PMID 34639032, 2021). "Patients with type 1 diabetes, who do not produce insulin, are deprived of the endogenous insulin regulation responsible for maintaining a constant level of glycemia." (PMID 33467392, 2021). "In clamp studies, our group found that obese youth with type 1 diabetes were more insulin resistant compared to non-obese peers with type 1 diabetes." (PMID 33828529, 2021).
type 1 diabetes (continued). "Type 1 diabetes, an autoimmune disease, is known as insulin-dependent diabetes which develops when pancreatic β-cells do not produce enough insulin and is accompanied by the destruction of these cells due to their own aggressive response." (PMID 33981318, 2021). "All islets in donors with type 1 diabetes were insulin-negative, although a few insulin-positive cells were found scattered in the exocrine parenchyma in 3/7 donors with type 1 diabetes." (PMID 34031141, 2021). "This study did not concern the change in angioarchitectonics in type 1 diabetes on the background of insulin therapy that requires another one." (PMID 33597584, 2021). "Many people with type 1 diabetes who are completely reliant on insulin for survival have no access to insulin." (PMID 34336550, 2021). "In one study, ghrelin levels were reported as being low prior to insulin treatment and non-responsive to meal tests in children with newly diagnosed type 1 diabetes." (PMID 34294136, 2021). "The autoimmune destruction of pancreatic β-cells leads to type 1 diabetes (T1D), in which there is a total lack of insulin secretion." (PMID 34959394, 2021). "We showed that people with type 1 diabetes and hospitalization received similar insulin regimens as type 1 diabetes comparisons and found no clear treatment differences before and after the event." (PMID 34277957, 2021). "Our finding of a decrease in basal insulin (and no changes in BMI) holds promise in maintaining optimal weight in nonobese adults with type 1 diabetes." (PMID 33628834, 2021). "Although donation programmes have shown some success in demonstrating that, if access to insulin is improved, type 1 diabetes does not need to be a death sentence in LMICs, these programmes need to be better integrated into the health system." (PMID 33483763, 2021). "Type 1 diabetes (T1D) is a chronic autoimmune condition in which the pancreas produces insufficient insulin or none at all." (PMID 32440803, 2021). "The discovery, purification, and subsequent demonstration that insulin administration could reduce blood and urine glucose levels and reverse ketoacidosis in individuals with type 1 diabetes (T1D) ultimately changed T1D from a terminal disease into a manageable chronic illness." (PMID 37745178, 2021). "As such, the low use rate in type 1 diabetes is not surprising, even more so as non-insulin antidiabetic treatment in type 1 diabetes is rare anyway." (PMID 34011313, 2021). "At present, the “one-size-fits-all” treatment for type 1 diabetes is exogenic insulin substitution therapy, but this approach fails to achieve optimal blood glucose control in many individuals." (PMID 33794915, 2021). "T1D, also known as insulin-dependent diabetes or juvenile diabetes, is a chronic disease characterised by little or no insulin produced by the pancreas." (PMID 33437514, 2020). "When untreated, the absence of insulin in type 1 diabetes results in unchecked lipolysis and ketogenesis, driving ketones to dangerously high levels, surpassing the plasma buffer capacity and impacting pH." (PMID 32872407, 2020). "Taken together, our data suggest that without ghrelin, STZ-treated mice modeling type 1 diabetes are unable to mount the usual CRR to insulin-induced hypoglycemia." (PMID 33042003, 2020). "In type 1 diabetes, beta (β) cells in the pancreas are destroyed due to an autoimmune response and without β cells to detect glucose, insulin is not released into the bloodstream." (PMID 32106464, 2020). "In general, the mean pancreas size of patients with type 1 diabetes is significantly decreased, probably resulting from lacking trophic effects of insulin." (PMID 32239341, 2020). "Moreover, albumin fusion technology has been used to obtain both long-acting insulin analogues and HSA-fusion products with Tregitope peptides and insulin peptides useful in the treatment of Type 1 Diabetes." (PMID 32992893, 2020).
type 1 diabetes (continued). "Type 1 diabetes (T1DM) is an autoimmune disease characterized by an immune-mediated destruction of pancreatic beta-cells, which leads to a lifetime dependence on exogenous insulin." (PMID 32192175, 2020). "Metformin added to insulin did not improve metabolic control or glucose variability in lean/normal-weight adolescents with type 1 diabetes." (PMID 33457425, 2020). "Many more children will die from malaria, diarrhoea diseases or acute respiratory infections than the number that will have type 1 diabetes and who will eventually die from lack of insulin." (PMID 32874425, 2020). "In conclusion, we describe a 19-year-old patient with classical newly diagnosed type 1 diabetes, which following fenofibrate treatment has been without insulin for 21 months." (PMID 32508930, 2020). "Based on her young age and absence of obesity, the patient was diagnosed with type 1 diabetes and insulin glargine 300 U/mL (Gla-U300) was started at 14 units/d." (PMID 32871938, 2020). "As far as we know, no human studies linking subcutaneous insulin treatment and pulmonary dysfunction in type 1 diabetes have been published." (PMID 32344939, 2020). "No other medication (except insulin for the patients with type 1 diabetes) was used by the study subjects." (PMID 32404378, 2020). "VDBP in pregnancy has also been linked to the development of type 1 diabetes mellitus (T1DM) in the offspring, a disease in which the pancreas does not produce insulin, resulting in a state of hyperglycaemia." (PMID 32443760, 2020). "The Leona M. and Harry B. Helmsley Charitable trust has recently invested in the funding of a large clinical study called ‘Type 1 Diabetes in Exercise’ (T1-Dexi study) that will yield a large publicly available dataset with time-matched CGM, insulin, food, and exercise data." (PMID 32517068, 2020). "A new version of UVA/PADOVA Type 1 Diabetes Simulator modifies Dalla Man’s model by incorporating glucagon secretion/action/kinetics and nonlinear increase in insulin dependent glucose utlization as BGL dips below the normal range." (PMID 32155149, 2020). "In type 1 diabetes patients, post‐prandial blood glucose values were not altered by adjunctive lixisenatide although prandial insulin dose fell." (PMID 32704555, 2020). "Insulin secretion was not represented, as the model was intended to simulate the type 1 diabetes condition." (PMID 33324238, 2020). "The low insulin-dose requirement in a long time and his non-acute presentation, in the childhood, of diabetes was unusual for type 1 diabetes." (PMID 31956423, 2020). "Leading reasons for exclusion were prior use of U-500 regular insulin; baseline A1C not in range or out of time window; no follow-up A1C available within 6 months; type 1 diabetes; and V-Go not initiated." (PMID 33202616, 2020). "One of the auto-immune diseases is a type I diabetes, in which a chronic inflammatory procedure eventually leads to beta-cell mortality and a lack of insulin production." (PMID 33235693, 2020). "This suggests that inflammatory changes in at least type 1 diabetes models are largely mediated by hyperglycemia, and not merely by changes in insulin or lipid levels." (PMID 33195459, 2020). "Significant reduction of GPR44 protein expression has been noted in insulin-negative human islets in pancreatic sections from individuals with long-standing type 1 diabetes." (PMID 32350565, 2020). "The detection of autoantibodies to insulin, GAD65, IA-2 and ZnT8 has proved valuable for prediction and diagnosis of type 1 diabetes, has provided insights into disease pathogenesis and into the heterogeneity of immune responses that appear in individuals developing the disease." (PMID 32314012, 2020). "While some studies report improvement in lipid profile, exercise capacity, and muscle fiber composition despite a sedentary lifestyle, others show no benefit of supplementation in the prevention of type 1 diabetes, and no improvements in insulin resistance." (PMID 32942582, 2020).